INS (insulin)
Diseases named in the same sentence as INS in open-access papers (continued):
Sharing a sentence is not in itself a finding about the gene and the disease.
Insulin resistance (continued). "Although no insulin sensitivity index has been thoroughly validated in CF cohorts, the Stumvoll index has been used previously by our group because of its capacity to screen for dynamic change in a glucose tolerance challenge, while the HOMA-IR mostly reflects fasting insulin resistance." (PMID 31318914, 2019). "In addition, insulin resistance such as type 2 diabetes of BAT occurring with ageing and weight gain will underestimate BAT activity as assessed with [18F]FDG scans, whereas FA and oxidative metabolism is not dependent on insulin sensitivity." (PMID 30804455, 2019). "Whether IMTG per se contributes to insulin resistance as indicated by other studies not involving GH is uncertain, and it is noteworthy that IMTG also increases following exercise in fit individuals without compromising insulin sensitivity." (PMID 31417493, 2019). "At the insulin-resistant state, no increase could be observed in AKT phosphorylation or GSK3β phosphorylation after insulin stimulation, indicating the successful induction of insulin resistance (lane 6 versus 5)." (PMID 31723029, 2019). "In the present study, we proved the hypoglycemic effect of IES on this animal model effectively, but IES did not improve insulin sensitivity in the ITT, which might be attributed to the fact that the GK rats was lean and might not exhibit serious insulin resistance." (PMID 30728346, 2019). "However, our studies with MitoPQ, where we observed insulin resistance without defects in Akt/TBC1D4, raise questions over whether such changes in insulin signaling are the primary driver of insulin resistance." (PMID 29599292, 2018). "While there were no data to confirm the presence of insulin resistance in the obese rats, these data in obese SHR/N-cp rats are of interest as this is an insulin-resistant phenotype and the results imply soy isoflavones are efficacious in reducing adiposity in an insulin-resistant state." (PMID 29601521, 2018). "Inhibition of DNL by skeletal muscle-specific FASN deletion improves systemic insulin sensitivity without altering adiposity, but decreases muscle strength, suggesting that DNL also plays important roles in skeletal muscle, especially in states of insulin resistance." (PMID 30274245, 2018). "Together, these data show that MitoPQ acutely impairs insulin-stimulated glucose uptake by blocking GLUT4 trafficking, supporting a role for mitochondrial oxidants, independent of mitochondrial function, in the induction of insulin resistance in adipose and muscle tissue." (PMID 29599292, 2018). "The abnormalities in lipid, insulin, and HOMA-IR, seen in this study confirm previous reports, which show that PCOS patients have altered lipidograms with high LDL-C, most probably due to the insulin resistance phenotype and altered BMI, rather than circulating androgen levels." (PMID 30131073, 2018). "Fenkci and colleagues reported that TAC values in women with PCOS were lower than the age- and BMI-matched controls and in their study the fasting insulin concentrations and TAC values had a negative correlation and they suggested that insulin resistance may alter the antioxidant system in PCOS." (PMID 29766146, 2018). "The improvement in β-cell function and decreased insulin resistance, although not statistically significant, might be attributed to the possibility that patients with YOD might be sensitive to metformin when insulin doses are lowered to maintain glycemic control." (PMID 29180640, 2017). "By transcriptome profiling in a large human cohort including non-obese and obese with or without insulin resistance, combined with functional evaluation in adipocyte cultures of specific genes, this study identifies KLF15 and SLC25A10 as potential modulators of adipocyte insulin sensitivity." (PMID 28570579, 2017).
Insulin resistance (continued). "We recognise that HOMA IR is not an ideal index of insulin resistance but in general population studies it is often impractical to perform euglycemic hyperinsulinemic clamp studies in all subjects and, in this case, HOMA IR and fasting insulin are satisfactory surrogate measures." (PMID 28546543, 2017). "There are a number of other models where insulin resistance develops independently of changes in DAG levels, and a recent study where an enzyme involved in phosphatidylethanolamine synthesis was disrupted in muscle, showed marked increases in muscle DAG without any change in insulin sensitivity." (PMID 29066734, 2017). "Differentiated cells were pre-incubated with palmitate (0.75 mM) for 16 h to induced insulin resistance then treated with different concentrations (1, 5 or 10 μM) of APL for 24 h or with 10 μM APL for different time intervals (6, 12 or 24 h) in the presence or absence of 100 nM insulin." (PMID 27391974, 2016). "However, the combined therapy fails to reduce fasting insulin (SMD −0.92; 95% CI −2.07 to 0.24; p=0.120), homeostasis model assessment of insulin resistance (SMD −1.15; 95% CI −3.36 to 1.06; p=0.309) and total testosterone (SMD −1.12; 95% CI −2.29 to 0.05; p=0.061)." (PMID 25818277, 2015). "However, the hyperinsulinemia induced by insulin treatment in the GK rats did not impair PKC activation in liver and could be explained by inhibition of insulin resistance in this animal model." (PMID 26398746, 2015). "Given the lack of an effect of increased plasma BCAA on inducing insulin resistance in the present study, the negative correlation reported previously between plasma BCAA and insulin sensitivity in humans may reflect impaired ability to metabolize BCAA in insulin-resistant individuals." (PMID 25781654, 2015). "Mean ± SD levels of FBG (118.5 ± 37.8 vs. 102.2 ± 32.0 mg/dL, p < 0.001), HbA1c (6.3 ± 1.2 vs. 6.0 ± 1.0 %, p = 0.013), insulin (15.7 ± 6.1 vs. 6.9 ± 2.3 μU/ml, p < 0.001), and HOMA-IR (4.5 ± 1.8 vs. 1.7 ± 0.5, p < 0.001) were significantly higher in patients with than without insulin resistance." (PMID 26542243, 2015). "Additionally, in mouse model of obesity related insulin resistance and visceral adipose tissue (VAT), a lack of perforin showed reduced insulin sensitivity and changed the inflammation status within the VAT lesions, suggesting an immunoregulatory role for perforin in this disease state." (PMID 25337791, 2014). "We did not see any improvements in insulin sensitivity following six weeks of supplementation with the combined formulation in our non-diabetic/insulin resistant cohort (mean HOMA-IR = 1.40), suggesting that a longer period of supplementation is needed to benefit those with insulin resistance." (PMID 25379688, 2014). "Furthermore, HFD-fed MCP-1 receptor i.e., CCR2-deficient mice (namely, ccr2−/− mice) do not normalize ATM content and insulin resistance to the levels of lean animals, suggesting that ATM recruitment and insulin resistance are also regulated by MCP-1/CCR2 independent signaling pathways." (PMID 24455420, 2013). "Furthermore, we found racial differences in the relationship between skin-fold thickness and both fasting insulin and HOMA-IR independent of % fat such that a thinner skin-fold relative to % body fat was detrimental to insulin and insulin resistance in Indian children, but unrelated in UK children." (PMID 22941936, 2012). "We hypothesize that although we found improvements in insulin sensitivity, the time of the study was not long enough to see a reduction in these MMP levels in people with severe insulin resistance, and that gene expression of MMPs and TIMP levels need to be measured along with MMPs." (PMID 23025537, 2012). "Interestingly, the beneficial effects of AICAR on adipose inflammation and insulin sensitivity were absent in MSKO mice fed HF diets, suggesting that the full capacity of AICAR to antagonize obesity-induced inflammation and insulin resistance requires myeloid SIRT1." (PMID 23183898, 2012).
Insulin resistance (continued). "Since the insulin and FFA levels did not change, and the HOMA decreased significantly after EA in STZ rats during ICT, we hypothesized that the EA-induced reduction in glucose was related to reduction in insulin resistance." (PMID 21754922, 2011). "Indeed, we showed that T3 administration actually preserves an intact response to glucose, and keeps plasma insulin levels in STZ-treated mice comparable to those in control mice; moreover, we showed that both STZ and STZ+T3 treated mice do not develop insulin resistance." (PMID 21637761, 2011). "However, insulin resistance, as measured indirectly by HOMA or insulin levels did not." (PMID 22046394, 2011). "Insulin levels were not measured during the GTT challenge; however, in the basal state they were higher (not lower) than control obese rats, suggesting relatively greater insulin resistance in these rats with the ability to compensate with hyperinsulinemia still intact." (PMID 20490358, 2010). "Our study was also intentionally focused on insulin resistance (HOMA‐IR) rather than pancreatic β‐cell function (HOMA2‐B); while this choice directly addressed our primary hypothesis, it limits a more comprehensive assessment of the interplay between pancreatic function, insulin and PV." (PMID 40955380, 2025). "However, FGF21 administration alone at 22°C did improve insulin resistance in LmnaADKO mice, but not other metabolic parameters, suggesting that FGF21 potentially interacts with nonshivering thermogenesis mechanisms to improve insulin sensitivity in these mice." (PMID 40663389, 2025). "Our study observed that glimepiride decreased insulin resistance without having a significant effect on IRAPe level this may be attributed to HOMA-IR, that used as indicator for insulin resistance, which calculated based on fasting insulin and fasting glucose concentration." (PMID 37072577, 2023). "Though the present study did not perform an insulin tolerance test (ITT), an indicative parameter to confirm insulin resistance, glyphosate-exposed hyperinsulinemia may be the reason for the development of insulin resistance and type-2 diabetes shown in the present findings." (PMID 38274944, 2023). "Moreover, the TyG index may be more reflective of muscle‐related IR and correlates strongly with homeostasis model assessment of insulin resistance (HOMA‐IR) in healthy nonobese individuals, as increased intramyocellular TG accumulation would impair glucose uptake and insulin signaling in muscle." (PMID 36071605, 2022). "The increase in phosphorylation of AS160 and AKT by insulin in the tunicamycin-treated Huh-7 cells failed to increase the uptake of glucose as seen in the vehicle treated cells, suggesting that AS160 and AKT phosphorylation may not be directly involved in the tunicamycin-induced insulin resistance." (PMID 36079898, 2022). "However, the decrease in insulin sensitivity was not accompanied by a reduction of skeletal muscle insulin signaling or total protein amount of GLUT4 or hexokinase 2; but of course, insulin resistance could have been induced through other pathways that we did not investigate." (PMID 35619221, 2022). "However, it is plausible that other mechanisms for inducing whole-body glucose intolerance and insulin resistance in adipo-rac1-KO mice may exist, considering that the contribution of WAT to insulin-dependent alteration in the blood glucose level is not so large." (PMID 34639094, 2021). "Therefore, AD-CON exhibited disrupted regulation of insulin secretion and attenuated insulin sensitivity at the hyperglycemic state in comparison to the Non-AD-CON, but LP, MP and SP prevented the disruption of insulin secretion and insulin resistance and was similar to Non-AD-CON." (PMID 25755673, 2015).
Insulin resistance (continued). "They found a significant elevation in fasting insulin levels and HOMA-IR values in the OSA group with an AHI greater than 5, while they could not detect any significant difference between obese and nonobese groups in terms of insulin level and insulin resistance." (PMID 26257957, 2015). "Thus, it is plausible that IHL accumulation could be associated with a relative beta-cell failure to adapt to increasing insulin resistance but that such a defect might not be apparent, because the concomitant reduction in HIE would lead to elevated circulating insulin levels." (PMID 24669786, 2014). "In addition, fasting hyperinsulinemia has been used as a surrogate estimate of insulin resistance according to various combinations of fasting insulin and the glucose concentration such as HOMA (homeostatic model assessment), but not the fasting insulin level per se." (PMID 22129309, 2011).
type 2 diabetes (14,525 papers, 1998 to 2026). "Its positive association with insulin sensitivity and inverse association with inflammatory markers in adults with obesity or Type II diabetes along with its purported benefit in mitochondria, liver, and intestines was recently reviewed." (PMID 41549605, 2026). "Amyloid fibrils formed by the islet amyloid polypeptide cause pancreatic beta-cell damage, resulting in reduced insulin secretion and type 2 diabetes." (PMID 41844597, 2026). "Using 2SMR, we evaluated causal links between these two CpGs, type 2 diabetes and several metabolic risk factors including fasting insulin and lipid levels." (PMID 41057690, 2026). "We investigated patient characteristics associated with acceptance of isCGM in individuals with type 2 diabetes treated with insulin." (PMID 42211598, 2026). "Adipocyte DNL is tightly regulated by the insulin signaling pathway, and insulin resistance — a hallmark of obesity and type 2 diabetes — disrupts glucose and lipid metabolism across multiple tissues." (PMID 41346765, 2026). "Methylation at these CpGs was associated with both type 2 diabetes and metabolic risk factors including BMI, fasting insulin and HDL-cholesterol." (PMID 41057690, 2026). "Clinical studies have shown that acute intensive insulin therapy causes a transient worsening of diabetic retinopathy in type 1 and type 2 diabetes." (PMID 41995437, 2026). "One of the basic questions that has arisen from clinical phenotyping of individuals with the SUR1 R1420H variation is the underlying mechanism for the switch in insulin secretion from hyperinsulinaemia in utero and infancy to type 2 diabetes later in life." (PMID 41291239, 2026). "Type 2 diabetes is characterized by metabolic dysfunction, primarily attributed to a loss of insulin sensitivity in peripheral tissues, resulting in poor glucose control." (PMID 41559866, 2026). "Methylation of the SREBF1 CpG (cg11851174) plausibly decreased HDL-cholesterol levels (pfdr=4.11 × 10−3) and increased both fasting insulin (pfdr=3.84 × 10−3) and risk of type 2 diabetes (pfdr=2.39 × 10−5)." (PMID 41057690, 2026). "As insulin is lipogenic in nature, we examined lipid patterns based on sex differences to better identify individuals at risk for type 2 diabetes." (PMID 41133433, 2026). "We found little evidence of causality for adipocyte differentiation and insulin content with adiposity and type II diabetes-related human phenotypes, respectively." (PMID 41390353, 2025). "This is important because people with obesity have reduced early and late phase insulin secretion, thereby raising the risk of type 2 diabetes." (PMID 40018087, 2025). "In rats on fructose-containing diets, the serum insulin concentration was higher at any energy density levels than it was in the corresponding glucose groups, suggesting a mild risk for type 2 diabetes." (PMID 40944136, 2025). "Prior research in type 2 diabetes has consistently demonstrated the potent glycemic control offered by insulin and the cardiovascular and renal benefits associated with SGLT2i, which is reflected in our results specific to the PTDM population." (PMID 40995094, 2025). "Obesity is closely associated with insulin secretion dysfunction and impaired insulin sensitivity, significantly increasing the risk of type 2 diabetes in both rodents and humans." (PMID 41007727, 2025). "The impairment of metabolic homeostasis that characterizes type 2 diabetes is caused in great part by insufficient insulin secretion to overcome peripheral insulin resistance." (PMID 40971442, 2025). "Characterized by elevated blood glucose levels, type 2 diabetes is associated with impaired insulin secretion and tissue sensitivity to insulin." (PMID 40507946, 2025). "Adequate consumption of fiber has several health benefits, such as reducing the risk of obesity, improving glycemic control and insulin sensitivity, and reducing the risk of type 2 diabetes and certain cancers." (PMID 40806151, 2025).